CXorf49B (chromosome X open reading frame 49B)
Synonyms: CXorf49
Tractability: PROTAC: ubiquitination databases record sites on it.
Gene: Protein-coding gene on chromosome X (71,763,349 to 71,767,204, forward strand). Ensembl gene ENSG00000215113.
Homologues: Orthologues: chimpanzee CXHXorf49B (98% identical), mouse Gm4779 (38% identical), rat Cxhxorf49 (37% identical), mouse 4933412E24Rik (36% identical), rat 4933412E24Rikl (34% identical), mouse 8030474K03Rik (33% identical), rat Cxhxorf49B (33% identical), rat Cxhxorf49l1 (31% identical), mouse Gm3858 (31% identical). Paralogues in human: CXorf49 (100% identical), CXorf49C (72% identical).
Diseases named in the same sentence as CXorf49B in open-access papers:
CXorf49B is named in the same sentence as 1 disease in open-access papers, as found by Europe PMC text mining. Sharing a sentence is not in itself a finding about the gene and the disease.
CXorf49B shares sentences with these, for which no sentence is quoted: lung adenocarcinoma (1 paper).